IL6 (interleukin 6)
Diseases named in the same sentence as IL6 in open-access papers (continued):
Sharing a sentence is not in itself a finding about the gene and the disease.
infection (continued). "There were significant reductions in IL-8, IL-6, and TNF-α production during infection in CFTR KO MDMs when compared to media alone or empty vector transfection." (PMID 32973772, 2020). "The abortive infection resulted in a long-lasting immunity in Mdr2−/− mice against infectious SPZ where neutrophils and IL-6 appear as key effector components along with CD8+ and CD4+ effector and central memory T cells." (PMID 33329563, 2020). "The changes of plasma IL-6 levels were similar as TNF-α changes, which increased after infection and were observed with a highest level after 24 h of infection, and then gradually decreased after treatment." (PMID 32221396, 2020). "The anti-inflammatory cytokines (interleukin-4 [IL-4], IL-6, and IL-10) and MCP-1/CCL2 were detected early after P. yoeliiyoelii 17XNL infection." (PMID 32958528, 2020). "To functionally demonstrate the role of IL-6, we impaired the expression of IL-6 by breeding Pax5+/- mice to IL-6+/− mice, which have significantly lower IL-6 serum concentrations, with the aim of testing whether IL-6+/-/Pax5+/- mice are more resistant to infection-induced B-ALL than Pax5+/- mice." (PMID 33154497, 2020). "Laboratory tests have shown that inflammatory factors such as IL‐6, IL‐1, IL‐10, and TNF‐α are up‐regulated during infection and can instigate an inflammatory response in the lower airways leading to lung injury in some instances." (PMID 32681537, 2020). "At 3 h post infection, both viable and heat-killed APEC strongly up-regulated gene expression of pro-inflammatory cytokines IL-1β and IL-6, chemokine IL-8 and the anti-inflammatory cytokine IL-10 compared to control cells that were mock-treated with medium." (PMID 32972448, 2020). "The infection of human AMs by the RSV stimulates the secretion of several proinflammatory cytokines, including IL-6, TNF-α, IL-1β, and IL-8." (PMID 32660087, 2020). "IFN-β, TNF-α, IL-6, and IL-12p40 were significantly upregulated in response to DIP infection compared to WT." (PMID 33298958, 2020). "Their resilience against infection, their major contribution of type I IFNs, the secretion of adequate amounts of TNF-α and IL-6, and the recruitment of NK cells to the lungs are key for the early control of infection." (PMID 32545470, 2020). "For instance, it was shown that infection with IAV H5N1 led to more pronounced induction of pro-inflammatory cytokines and chemokines (IP-10, IFN-β, IL-6, RANTES) in human primary epithelial cells, compared with infection with H1N1." (PMID 33255985, 2020). "Of note, although the serum level of IL-6, CXCL1, and CCL7 in klotho WT mice decreased at 3 days post-infection, those in klotho KO mice was maintained until 3 days post-infection." (PMID 33329595, 2020). "A modest but statistically significant release of IL-6 and TNF-α in response to rVSVΔM51 was observed at 12 h post-infection, which peaked by 16 h and declined by 20 h post-infection." (PMID 33261178, 2020). "Compared with the CK group, IL-6, IL-1β, TNF-α and IL-17 all increased in the MC group under the infection of E. coli O157, while the GOS group reversed this increase under intervention." (PMID 33233359, 2020). "Based on these data, IL-6, IL-1β, and TNF-α elevation during fetal infection stimulates LRG expression in fetal hepatocytes to increase the umbilical cord serum LRG levels." (PMID 33211747, 2020). "Our results show that incubation of HRV with LL-37 alters the virus-mediated gene expression of IL-8, IL-6, and CCL5 mRNA in response to infection." (PMID 32117246, 2020). "In the study, after infection, the levels of TNF-α, IL-6, and IL-1β in obese mice increased for a short time, and then decreased, which is conducive to reducing the inflammatory immune damage of the spleen and promoting the repair effect." (PMID 32104715, 2020). "At 1 week post-infection, when T. gondii infection is systemic, mice had elevated circulating IFN-γ, IL-1β, IL-6, and TNF-α compared to uninfected controls (grey background)." (PMID 32973293, 2020).
infection (continued). "Infection with either NH/P68 and 22653/14 ASFV resulted in a reduced ability of moMΦ to release the same cytokines (IL-6, IL-12, TNF-α) in response to stimulation with Pam2Cys lipopeptide." (PMID 32178332, 2020). "The modeling revealed that the identified cytokines to some extent was dependent on the infectious agent, but some cytokines were consistently identified to predict the type of infection, i.e., MCP-1, Eotaxin, RANTES, GM-CSF, IL-6, and IL-10." (PMID 33363054, 2020). "As expected, mice infected with Cr had increased colonic tissue expression of several cytokines associated with a pro-inflammatory Th1/Th17 immune response including IL-17A, IL-22, IL-6, IL-1β, TNF-α, and IFN-γ on day 12 after infection." (PMID 33076301, 2020). "Seven cytokines were identified as infection-specific, showing elevated concentrations in the septic TKR cohort compared to both the aseptic TKR and primary TKA cohorts: IL-1α, IL-1β, IL-6, IL-8, MCP-1, MIP-1α, and MIP-1β (p < 0.05)." (PMID 32867801, 2020). "There were numerous abnormal infection-related biomarkers in sera of the diabetic patients, hs-CRP, ESR, PCT, and IL-6 were beyond the normal range." (PMID 33071977, 2020). "During infection, PCT can be produced by several cell types and many organs in response to pro-inflammatory cytokines (e.g., tumor necrosis factor-α and interleukin-6)." (PMID 32160878, 2020). "In terms of infection-related serum markers, studies show that C-reactive protein (CRP), IL-6, and erythrocyte sedimentation rate (ESR) are significantly increased in many patients." (PMID 33082858, 2020). "The levels of inflammatory cytokines of IL-6 and TNF-α and infection-related biomarker of SF were also significantly increased with the disease progression (P = 0.038, 0.048 and 0.022, respectively)." (PMID 32841294, 2020). "Morphine-exposure during SHIV 3NF-κB infection further suppressed IL-6 transcript levels, while during SHIV 4NF-κB infection an increase in IL-6 transcript levels was noted." (PMID 32076422, 2020). "SARS-CoV infection induces NF-κB targeted genes, like IL-6 and IL-8, early in the infection, while IFN-I induction by IRF3 and IRF7 is delayed until 48 h after infection." (PMID 33377937, 2020). "Inflammatory markers, such as C-reactive protein (CRP), interleukin-6 (IL-6), and tumor necrosis factor-α (TNF- α) are shown to markedly increase in response to infection and tissue damage, as well as in active state of disease." (PMID 32731638, 2020). "To evaluate variations in immune response according to KoRV subtype infection status, we measured expression levels for CD4, CD8b, IL-6, IL-10, and IL-17A in RNA isolated from unstimulated koala PBMCs." (PMID 33316950, 2020). "An interesting finding was that some mediators were more affected by TLR2 loss in the brain compared to the galea, including IL-1β, CCL2, TNF-α, IL-6, and CXCL2, which was particularly evident at day 14 post-infection." (PMID 32290861, 2020). "IFNα, IFNβ, IFNλ1, Rig-I, IRF3, IRF7, OAS-1, MxA, IL6, IL8, and TNFα expressions were increased at either day 1 or day 2 in HFDPCs post-infection or on both days." (PMID 32121148, 2020). "The delivery of exosomes recovered from the airways of influenza virus-infected mice resulted in the production of IL-6, MCP-1 and TNF, which was a very similar inflammatory profile to that observed following direct infection with influenza virus." (PMID 32477358, 2020). "Mabc-R-mediated mRNA generation of Tnf, Il6, and Cxcl2 was significantly increased in BMDMs from SIRT3 KO mice compared to SIRT3 WT mice after infection in a time-dependent manner." (PMID 32835604, 2020). "Levels of IL-1β, IL-6, CCL2, CCL3, CXCL1, and CXCL2 were significantly greater 6 h following infection than in mock-infected mice (P < 0.05) but were similar among wild-type, CCR2−/−, and Nr4a1−/− mice." (PMID 31818962, 2020).
infection (continued). "It was observed that after the infection with H. pylori, secretion of TNF-α, IL-6 and IL-8 increased considerably in AGS cells compared to basal levels." (PMID 32230910, 2020). "Inflammatory cytokines such as interleukin-6 (IL-6), C-reactive protein (CRP), and procalcitonin (PCT) have clinical significance as predictive or prognostic markers of infection." (PMID 32711473, 2020). "Yet, infection of CD200R1 KO PCLS with live CHA and simultaneous inhibition of MARCO significantly decreased IL6 expression compared to live CHA-infected CD200R1 KO PCLS with functional MARCO signaling." (PMID 33250899, 2020). "Yet, between 38–48 days post infection, all tested pro-inflammatory cytokines (IFN-γ, TNF, IL-6 and MIF) increased or remained high in TgAlbCre-IL10-/- mice, but not in the other strains." (PMID 32012211, 2020). "Here, macrophages display a decreased T cell activation capacity in response to infection with Mycobacterium bovis BCG (Bacillus Calmette–Guérin), which is reversed by preincubation with neutralizing antibodies against IL-6." (PMID 33334075, 2020). "Infection of macrophages with MAP increased iNOS expression (13.09 ± 0.94 vs. 5.11 ± 0.8 in uninflected cells), IL-6 (38.43 ± 1.2 vs. 18.5 ± 1.8 in uninfected cells), and TNF-α (0.54 ± 0.075 vs. 0.27 ± 0.08 in uninflected cells)." (PMID 32370298, 2020). "Analysis of serum IL-6 and TNFα concentrations in PBS treated animals at day 0, day 8 and day 12 post-infection showed that concentrations of both cytokines increased marginally but not significantly overall by day 8 post challenge." (PMID 32584899, 2020). "Upon infection, TNF-α, IL-4, and IL-6 expressions heightened, while IL-3 and IL-1β only appeared in trace amounts." (PMID 32943637, 2020). "After 2 h of infection with Mtb WT, there was a significant upregulation of immune modulators such as TNF, IL-1A, IL-1B and IL-6." (PMID 32938685, 2020). "We found that the expression of CCL2, CCL5, IL-6, and TNF-α was inhibited through the course of infection in U0126-pretreated cells and that viral RNA abundance was also decreased in U0126-pretreated cells." (PMID 31694957, 2020). "In this model we observed a significant increase in total neutrophils in Peli1−/− animals at 72 h post-instillation, and again saw higher levels of IL-6 and TNFα in BAL fluid at both 72 and 96 h post-infection." (PMID 32984077, 2020). "This pattern of infection was also reflected in the cytokine profiles of infected cells; IFN-α2a, IL-6, and TNF-α production was significantly enhanced 24 h after infection of M0 and M2 macrophages and was only modestly enhanced in the M1 population." (PMID 32088771, 2020). "Infection in pregnant mice induced a 1.6-fold reduction of KC, 1.7-fold reduction in MIP-1α, 1.4-fold reduction of RANTES, 2.4-fold reduction of IL-6 and 2-fold reduction of IL-12(p40) at 4 DPI, compared to non-pregnant controls." (PMID 32922392, 2020). "During infection, CSF3 works along with IL3, IL6, and CSF2 to stimulate neutrophil granulopoiesis in the bone marrow to restore neutrophil homeostasis." (PMID 33362771, 2020). "In agreement with the gene expression data, infection with Mtb WT significantly increased the secretion of IFN-α, TNF-α, IL-8, MCP-1, IL-1-α, IL-6 and MIP1-α and MIP1-β." (PMID 32938685, 2020). "Using Luminex multiplex immunoassay, we measured cell culture supernatant fluid levels of the cytokines TNF-α, IL-1β, IL-6, IL-10, RANTES, and IL-8 at 6 h and 24 h following infection." (PMID 32994292, 2020). "IL-8 does not only correlate with the severity of infection, but is also appears to be more efficient in diagnosing EOS prior to other markers (IL-6, IL-10)." (PMID 33419284, 2020). "By contrast, in patients with critical disease, the beneficial effect of anti-IL-6/IL-6R/JAK antibodies on mortality became indistinct, and resulted in an evident trend of increased secondary infection rates." (PMID 33384605, 2020).
infection (continued). "We subsequently analyzed the kinetics of the most intensive pro-inflammatory cytokines including TNF-α, IL-1β, IL-6, and IL-18 in sera of pigs upon SY18 infection." (PMID 33553280, 2020). "In a mouse model of 2009 H1N1 pandemic influenza, the S1p1 receptor agonist significantly inhibited synthesis of IL-1α, IL-1β, IL-6, IL-10, MCP-1, TNF-α, and GM-CSF, and reduced deaths from lethal infections by more than 80%." (PMID 32574268, 2020). "Many of these cytokines such as IL1, IL2, IL6, IL10, IL17, IL23, TNF-α, TGF-β, IFN-γ, CXCL12, and CXCL4 are secreted both at the site of infection and in the general blood circulation." (PMID 33569347, 2020). "Third, markers of inflammation, including neutrophil infiltration and the production of proinflammatory cytokines, such as TNF-α, IL-1β and IL-6, production in the BALF were determined 24 h post-infection." (PMID 32197534, 2020). "In this study, we did such work and found that infection with C. psittaci will increase the replication of H9N2, decrease the iNOS–NO pathway, and raise the IL-6 and IL-10 expression of HD11 cells by H9N2 infection." (PMID 32326284, 2020). "Ms_YrbE3A induced IL-6 and TNF-α expression in RAW264.7 at various time points starting from 2 h after infection." (PMID 32316659, 2020). "At 4 days post-infection (dpi), lung samples were isolated to measure the concentration of inflammatory cytokines IFN-γ and IL-6." (PMID 32459823, 2020). "IL-6 is known to induce gene expression and release of CRP from the liver in response to inflammation or infection." (PMID 33198109, 2020). "Several human VL studies have demonstrated elevated serum levels of IL-4, IL-6, IL-10, IL-12, IL-13, IFN-g, and TNF-a in active disease compared to asymptomatic infection." (PMID 32321156, 2020). "IAV-induced transcriptional levels of IFN-α, TNF-α, IL-12, IL-6, IFN-α, and RANTES were reduced following factor H treatment for the H1N1 subtype at 6 h post-infection." (PMID 32269562, 2020). "Along with IL-6 and the soluble IL-2 receptor, TNF-α levels increase early in the infection and remain elevated throughout the infection." (PMID 32961074, 2020). "The expressions of IFNα, IFNβ, IFNλ1, Rig-I, OAS-1, MxA, IL6, IL8, and TNFα were increased at either day 1 or day 2 in WS1 post-infection or on both days." (PMID 32121148, 2020). "Upregulation of pro-inflammatory cytokines such as TNF-α and IL-6 commonly observed following H7N9 infection in both cell culture and in severe human cases, which follow similar patterns of pathogenesis to infections with HPAI H5N1 viruses." (PMID 33072098, 2020). "Serum levels of pro-inflammatory cytokines were similar among the participants with different infection status (TNF-α; p = 0.290, IL-1β; p = 0.442, IL-6; p = 0.686, IFN-γ; p = 0.801, IL-8; p = 0.546, IL-12; p = 0.154)." (PMID 33317454, 2020). "The tat induces the expression of monocyte chemoattractant protein-1 (MCP-1), which attracts monocytes to the site of infection and induces the synthesis of tumor necrosis factor alpha (TNF-α), nuclear factor kappa- B (NF-κB) and interleukin-6 (IL-6)." (PMID 32722629, 2020). "An increase in expression of IFN-β and IFN-λ, as well as pro-inflammatory cytokines and chemokines (IL-6, IL-8, IP-10, CXCL-11, RANTES), was noted one day after infection." (PMID 33255985, 2020). "Most importantly, blocking Notch signaling with DAPT reduced MAP infection and the inflammatory response which strongly indicates that Notch signaling is essential for IL-6 and MCL-1 expression in response to intracellular infections such as MAP or M. bovis." (PMID 32635645, 2020).
infection (continued). "On the contrary, nicotine in CD active smokers associated with bacterial infection induce M1-macrophage polarization, upregulation of iNOS, IL-6, and TNF-α, downregulation in CD206, IL-10, decrease in caspase-3 activity, and increase in infection burden." (PMID 32370298, 2020). "At three days after treatment, TNF-α, IL-6, and MCP-1 in the serum of the amphenmulin treatment group were significantly decreased than those of the infection group (p < 0.05)." (PMID 32079232, 2020). "In the late stage of infection, IL-6 and G-CSF levels in the A/Zhejiang/DTID-ZJU01/2013(H7N9) infection group had decreased to normal levels." (PMID 32267217, 2020). "In fact, cultured human bronchial epithelial cells produced significant amounts of IL-6, IL-8, and CCL5 upon infection with A/Shisen/2/93 (H3N2) virus detectable from 24 h after infection." (PMID 33062077, 2020). "IL-6 KO infected mice produced lower levels of the proinflammatory cytokines IFN-γ and TNF-α, at 1 week and 6 weeks post-infection compared to wild-type infected animals." (PMID 33322581, 2020). "The levels of IL-1β, IL-6, and TNF-α were initially detected at 4 h after infection and gradually increased in a time-dependent manner." (PMID 32433516, 2020). "It is well-known that PCT, IL-6, CRP, and also IPF are strongly related with infections; hence, we also examined the results after excluding patients who developed an infection during the first 3 days after surgery." (PMID 37360622, 2020). "It is well known that C. acnes induces the release of proinflammatory cytokines and chemokines, including IL-1β, IL-6, interferon (IFN)-γ, TNF-α, and IL-8 at the onset of infection." (PMID 32867396, 2020). "Many immune cells in the blood secrete TNF-α and IL-6, especially during infection and inflammation, and monocytes and macrophages in the peripheral blood and tissues mainly secrete large amounts of TNF-α and IL-6." (PMID 32976531, 2020). "Infection of the keratinocytes resulted in strong bacterial damage of HaCaT cells along with low cellular ATP levels and high release of LDH, IL-6, and IL-1α after 24 h and 48 h." (PMID 33302597, 2020). "The release of select inflammatory proteins (IL6, IL8, CSF3, IL1β, CXCL10, and ICAM1) into the culture medium of HEKs and SCC cells following infection with C. t." (PMID 31912662, 2020). "Following USUV infection, we showed secretion of CXCL10, CCL5, and IL6 in apical compartments from 4 to 10 dpi, but the secretion level decreased with time." (PMID 32324736, 2020). "To determine if CFTR KO alters macrophage cytokine production, we measured production of 5 cytokines (IL-8, IL-1β, IL-6, IL-10, and TNF-α) at baseline and in response to infection with B. cenocepacia." (PMID 32973772, 2020). "In the case of infection by SARS-CoV-2, there is a greater production of IL-6 and GM-CSF in the peripheral blood by CD14+ CD16+ monocytes." (PMID 33193377, 2020). "Transcriptional levels of IFN-α, TNF-α, IL-12, IL-6, and IFN-α were upregulated, while RANTES was downregulated following factor H treatment for the H1N1 subtype at 6 h post-infection." (PMID 33488586, 2020). "CXCL2 (MIP‐2) and CXCL1 (KC), which are responsible for the infiltration of neutrophils and monocytes, were suppressed at the beginning of infection (6 h), whereas inhibition of CCL2 (MCP‐1), TNF‐α, IL‐6, IL‐1β and IL‐17A appeared after 24 h." (PMID 33014369, 2020). "infection, whereas the corresponding early responding genes in SCC cells were IL10, IL1β, IL1α, TNF, CXCL10, CXCL1, HBEGF, IL6, and CSF3." (PMID 31912662, 2020). "High levels of TNF-α, IL-6, and IFN-γ are produced from T cells responses, and they contribute to the activation of the immune system against infection." (PMID 33212789, 2020).